PCBP1 (poly(rC) binding protein 1)
Description:
Single-stranded nucleic acid binding protein that binds preferentially to oligo dC. Together with PCBP2, required for erythropoiesis, possibly by regulating mRNA splicing (By similarity). (Microbial infection) In case of infection by poliovirus, plays a role in initiation of viral RNA replication in concert with the viral protein 3CD.
Synonyms: HNRPE1; hnRNP-E1; HNRPX; hnRNP-X; HEL-S-85
Tractability: PROTAC: UniProt records ubiquitination sites on it; ubiquitination databases record sites on it; its protein half-life has been measured.
Gene: Protein-coding gene on chromosome 2 (70,087,477 to 70,089,203, forward strand). Ensembl gene ENSG00000169564.
Subcellular location: Nucleus; Cytoplasm
Subcellular location (Human Protein Atlas): Nuclear speckles; Cytoplasmic bodies; Cytosol; Nucleoplasm
Pathways (Reactome):
Metabolism of RNA: Processing of Capped Intron-Containing Pre-mRNA; mRNA Polyadenylation; mRNA Splicing - Major Pathway
Disease: Dengue Virus-Host Interactions
Gene Ontology:
Molecular function: cadherin binding; mRNA binding; protein binding; RNA binding; single-stranded DNA binding; DNA binding; DNA-binding transcription factor activity, RNA polymerase II-specific; nucleic acid binding; sequence-specific single stranded DNA binding
Biological process: viral RNA genome replication; positive regulation of transcription by RNA polymerase II
Cellular component: cytoplasm; cytosol; extracellular exosome; membrane; nuclear speck; nucleoplasm; nucleus; postsynaptic density
Genetic constraint (gnomAD): Loss-of-function variants: 0 observed, 19.08 expected, observed/expected ratio (o/e) 0, 90% interval 0 to 0.16. The synonymous counts are far from expectation, so gnomAD's model fits this gene poorly and the ratio says little. Missense variants: 244 observed, 500.85 expected, observed/expected ratio (o/e) 0.49, 90% interval 0.44 to 0.54. Synonymous variants: 284 observed, 208.59 expected, observed/expected ratio (o/e) 1.36, 90% interval 1.24 to 1.5.
Homologues: Orthologues: chimpanzee PCBP1 (100% identical), guinea pig PCBP1 (100% identical), macaque PCBP1 (100% identical), mouse Pcbp1 (100% identical), rabbit PCBP1 (100% identical), rat Pcbp1 (100% identical), pig PCBP1 (90% identical), Drosophila melanogaster mub (48% identical), Caenorhabditis elegans pes-4 (35% identical), Drosophila melanogaster ps (23% identical), Caenorhabditis elegans fubl-3 (20% identical), Drosophila melanogaster Psi (19% identical), and 5 more. Paralogues in human: PCBP2 (84% identical), PCBP3 (68% identical), PCBP4 (51% identical), HNRNPK (32% identical), IGF2BP2 (29% identical), FUBP1 (27% identical), FUBP3 (27% identical), KHSRP (27% identical), IGF2BP1 (26% identical), IGF2BP3 (26% identical), NOVA2 (24% identical), NOVA1 (22% identical).
Diseases named in the same sentence as PCBP1 in open-access papers:
PCBP1 is named in the same sentence as 79 diseases in open-access papers, as found by Europe PMC text mining. Sharing a sentence is not in itself a finding about the gene and the disease. The quoted sentences say what the papers report.
breast carcinoma (13 papers, 2017 to 2026). "Conversely, knockdown of PCBP1 in turn accelerates p27 mRNA degradation, causes low p27 (cell cycle inhibitor) protein levels and leads to the development of breast cancer." (PMID 36052258, 2022). "Here, we identify Poly(rC) Binding Protein 1 as a tumor suppressor that amplifies cGAS-STING signaling in breast cancer." (PMID 41501525, 2026). "The most frequent RBP (by frequency) per our analysis–PCBP1 –has also been shown to regulate EMT in breast cancer." (PMID 38838009, 2024). "The TF SPI1 and the RBPs ESRP1, ESRP2 and PCBP1 featured frequently in detected statistical interactions, suggesting additional mechanistic roles for these proteins in breast cancer." (PMID 38838009, 2024). "Given the role of PCBP1 in our mouse model of mammary carcinoma and the increase in FAM3C and LIFR expression following loss of PCBP1, we sought to identify the mechanism(s) governing LIFR expression in mammary epithelium." (PMID 37927213, 2023). "In prostate and breast cancers, PCBP1 expression was significantly upregulated and correlated with poor outcomes, and PCBP1 acts as a pro-oncogenic factor." (PMID 35287546, 2022). "In breast cancer, knockdown of PCBP1 enhances the stemness of breast cancer cells and promotes breast cancer invasion and metastasis by regulating the ILEI/LIFR signalling pathway." (PMID 35907982, 2022). "Recently, PCBP1 has been shown to be a negative regulator of ovarian carcinoma, breast cancer, gastric cancer, and other cancers." (PMID 35907982, 2022). "HOTAIR, the most studied lncRNA, interacts with 26 various functional elements, such as EZH2 and PCBP1, and 40 diseases, including gastric cancer, breast cancer and colon cancer." (PMID 30759219, 2019). "A recent study of breast cancer highlighted the regulatory role of RNA binding by PCBP3 (paralog of PCBP1 along with PCBP2) on mRNA stability and induction of epithelial-mesenchymal transition (EMT)." (PMID 29335020, 2018). "Correlation of PCBP1 with p27 is also found in the tamoxifen, doxorubincin and lapatinib resistant breast cancer cells of GEO database." (PMID 30086790, 2018). "As a member of the PCBP family proteins, PCBP1 is reported to be reduced in lung cancer, cervical cancer, breast cancer, colon cancer, and liver cancer, suggesting that altering PCBP1 expression may become a possible therapeutic strategy." (PMID 37426488, 2023). "It has been reported that PCBP1 expression is downregulated in breast cancer." (PMID 36052258, 2022). "In addition, PCBP1 confers drug sensitivity in colorectal cancer, prostate cancer, and breast cancer." (PMID 35907982, 2022). "Increasing evidence indicates that PCBP1 could be involved in repressing carcinogenesis, as downregulation of PCBP1 has been observed in multiple cancers, including cervical cancer, liver cancer, breast cancer cells, colon cancer and lung cancer." (PMID 30086790, 2018). "PCBP1 and p27 expression were analyzed by data from GEO database, and high expression of PCBP1 and p27 were observed in Tamoxifen (GSE26459), Doxorubicin (GSE24460) and Lapatinib (GSE16179) sensitive breast cancer subclones (n indicates the analyzed cell subclone numbers)." (PMID 30086790, 2018).
gastric cancer (10 papers, 2017 to 2026). A primary or metastatic malignant neoplasm involving the stomach. "Cumulatively, our findings highlight both loss of miR-3978 expression and PCBP1 as potential prognostic biomarker in gastric cancer patients." (PMID 29138420, 2017). "PCBP1 mRNA was downregulated 12.2 ± 1.55 folds in metastatic tissue compared with normal peritoneum, indicating that loss of PCBP1 expression might be the pervasive mechanism dictating its attenuation of tumor suppressor role in the context of peritoneal metastasis in gastric cancer." (PMID 29138420, 2017). "Even so, the Kaplan–Meier survival analysis demonstrated that improved mOS was observed in gastric cancer patients with high PCBP1 expression (Log-rank P < 0.05)." (PMID 35100974, 2022). "In conclusion, the present study elucidated that depletion of C12orf48 attenuates growth and metastasis processes of gastric cancer via up-regulation of PCBP1." (PMID 35100974, 2022). "More importantly, we found that PCBP1, a novel tumor suppressor gene, is inhibited by C12orf48 in gastric cancer." (PMID 35100974, 2022). "Our findings indicate that depletion of C12orf48 inhibited gastric cancer growth and metastasis via up-regulating PCBP1." (PMID 35100974, 2022). "Studies showed that PCBP1 protein was significantly downregulated in various primary and metastatic cancers, including gastric cancers, while its mRNA level remained unchanged in most cancer tissues." (PMID 35100974, 2022). "Expression of both PCBP1 and miR-3978 is downregulated whereas expression of legumain is upregulated in gastric cancer patients with peritoneal metastasis." (PMID 30246786, 2018). "Given that PCBP1 has been indicated in the pathogenesis of a wide variety of cancers, we decided to further pursue the role of PCBP1 in peritoneal metastasis of gastric cancer." (PMID 29138420, 2017). "In the current study, our experimental results show that miRNA-3978 and PCBP1 is downregulated in gastric cancer patients with peritoneal metastasis." (PMID 29138420, 2017). "Our experiments showed a direct interaction of PCBP1 and miR-3978 that are repressed during peritoneal metastasis of gastric cancer." (PMID 29138420, 2017). "If a similar scenario is observed in gastric cancer, it will have to be determined what alternate nodes in the miRNA biogenesis pathway are being modulated by differential PCBP1 expression, and vice versa." (PMID 29138420, 2017). "Our results thus indicate that interaction or presence of both PCBP1 and miR-3978 is essential to potentiate chemosensitivity to docetaxel treatment in gastric cancer patients with peritoneal metastasis." (PMID 29138420, 2017). "This collection of results demonstrated that PCBP1 could inhibit the malignant behavior of gastric cancer cells." (PMID 37752765, 2023). "he current study demonstrated that the downregulation of Siva-1, which functions as a regulator of MDR1 and MRP1 gene expression in gastric cancer cells by inhibiting PCBP1/Akt/NF-κB signaling pathway expression, enhanced the sensitivity of gastric cancer cells to certain chemotherapies." (PMID 37303491, 2022). "In view of this, we investigated whether the expression profile of PCBP1 was altered in gastric cancer tissues and its correlation with the clinical significance." (PMID 35100974, 2022). "Moreover, the tumorigenicity of cancer cells, including gastric cancers, was attenuated once PCBP1 was overexpressed." (PMID 35100974, 2022). "PCBP1 expression mimicked miR-3978 expression across gastric cancer patients." (PMID 29138420, 2017). "CircMAP2K2 regulates the PCBP1/GPX1 axis through proteasome‐mediated degradation, resulting in an epithelial‐to‐mesenchymal transition (EMT)‐like phenotype, and activated AKT/GSK3β signaling pathway enhances proliferation and metastasis of gastric cancer." (PMID 37752765, 2023).
gastric cancer (continued). "We also employed the GEPIA website and TMA immunohistochemistry to analysis the expression profile of PCBP1 between gastric cancer tissues and non-neoplastic gastric epithelium tissues." (PMID 35100974, 2022). "It will be interesting to determine if miR-3978 and PCBP1 share similar promoter architecture and whether they are both regulated by PAK1 in the context of peritoneal metastasis in gastric cancer." (PMID 29138420, 2017). "Furthermore, we found that PCBP1 overexpression contributes to up-regulation of mesenchymal marker vimentin while down-regulation of epithelial marker E-cadherin both in-vitro and in-vivo, which reversed C12orf48-mediating EMT in gastric cancer." (PMID 35100974, 2022). "In addition, suppression of PCBP1 expression or post-translational modification can increase the translation of genes and long non-coding RNAs (LncRNAs) which were required for EMT and metastasis in different cancers, including gastric cancer." (PMID 30246786, 2018). "However, not much is known beyond expression pattern of legumain and PCBP1 during peritoneal metastasis of gastric cancer patients." (PMID 30246786, 2018).
ovarian carcinoma (10 papers, 2014 to 2023). A malignant neoplasm originating from the surface ovarian epithelium. "These proteins were significantly upregulated in malignant tumors and have all been linked to cancer previously and all but one, PCBP1, specifically to ovarian cancer." (PMID 25265318, 2014). "In the cBioPortal database, almost all neighboring genes connected to PCBP1 have altered expression in more than 20% of the serous ovarian cancer samples (data not shown) providing further evidence of a critical role for PCBP1 in the pathophysiological processes underlying malignant ovarian tumors." (PMID 25265318, 2014). "PCBP1 promotes ovarian cancer migration and invasion in vitro by inhibiting TRIM56 translation, reducing its protein levels, thereby inducing Vimentin expression." (PMID 36902478, 2023). "To further confirm the clinical relevance of PCBP1 to ovarian cancer progression, we examined PCBP1 expression state by immunohistochemistry (IHC) in 90 cases of ovarian cancer, compared with the 10 corresponding cancer adjacent ovarian tissues among them." (PMID 32922440, 2020). "PCBP1 downregulation promotes cell proliferation and tumorigenicity of ovarian cancer cells both in vitro and in vivo." (PMID 32922440, 2020). "Our IHC results were scored and indicated that PCBP1 was more detectable in cancer adjacent tissues than ovarian cancer samples." (PMID 32922440, 2020). "Overall, we found that PCBP1, p62, and Caspase-8 expression levels were correlated with each other in ovarian cancers." (PMID 32922440, 2020). "Statistically significant decreased PCBP1 expression was also found in ovarian cancer samples with positive lymph node and distant metastasis statues, compared with those with negative status." (PMID 32922440, 2020). "To thoroughly validate the relationship between PCBP1, p62 and apoptosis in tumor samples, we use the same batch of ovary cancer samples to check these 3 protein expressions at same time." (PMID 32922440, 2020). "Overexpression of PCBP1 promoted the migration and invasion of ovarian cancer cell SKOV-3." (PMID 35287546, 2022). "In ovarian cancer, PCBP1 inhibits tumour progression by regulating the mRNA stability of p27." (PMID 35907982, 2022). "PCBP1 expression and clinicopathologic characteristics of ovarian cancer patients." (PMID 32922440, 2020). "Moreover, similar to PCBP1 expression pattern in ovarian sample, we observed statistically significant p62 expression decrease in ovarian cancer samples vs. the adjacent samples." (PMID 32922440, 2020). "Moreover, we summarized the correlation between PCBP1 expression and clinicopathologic variables of patients with ovarian cancer." (PMID 32922440, 2020). "Further experiments are warranted to unravel the precise mechanism of PCBP1 in ovarian cancer." (PMID 25265318, 2014). "Pathway and subsequent interactome analysis also highlighted common regulators in serum and tissue samples, suggesting a yet unknown role for PCBP1 in ovarian cancer pathophysiology." (PMID 25265318, 2014). "Importantly, clinical ovary cancer sample analysis consistently validates the relevance of PCBP1 expression to both p62/SQSTM1 and caspase-8 to overall survival, and indicates PCBP1 may be a master player to repress tumor initiation." (PMID 32922440, 2020). "In ovarian cancer, RNA-affinity pulldown using biotinylated TRIM56 3’-UTR combined with mass spectrometry has found PCBP1 as the most differentially binding protein." (PMID 35287546, 2022). "Poly(rC) binding protein 1 (PCBP1) protein binds to p27 mRNA and enhanced its stability in ovarian cancer cells, thereby enhancing p27 mRNA translation, inhibiting cell cycle and promoting apoptosis." (PMID 30744670, 2019). "In addition, our results implicate an as yet unknown role for PCBP1 in ovarian cancer." (PMID 25265318, 2014).
ovarian carcinoma (continued). "In this study, although the ovary cancer here is focused, the consistent results observed in CHO cell line and two colon cancer cell lines could to suggest the general observation of PCBP1 in autophagy modulation." (PMID 32922440, 2020). "To thoroughly investigate the mechanism of PCBP1 against tumor formation, we adopted a strategy to capture all PCBP1-bound mRNAs by crosslinking PCBP1 to RNA molecules and immunoprecipitating them for sequencing identification (indicated as RIP-seq) in human ovarian cancer A2780 cells." (PMID 30086790, 2018).
colorectal cancer (8 papers, 2017 to 2026). A primary or metastatic malignant neoplasm that affects the colon or rectum. "A past study showed that knockdown of PCBP1 sensitized human oxaliplatin-resistant colorectal cancer cells (HT-29/L-OHP) to oxaliplatin, whereas overexpression of PCBP1 increased oxaliplatin resistance in colorectal cancer cells." (PMID 37303491, 2022). "To provide in vivo evidence that increased PCBP1 expression is associated with L-OHP resistance, we analyzed 40 tumor samples from colorectal cancer patients among which 20 cases were L-OHP sensitive and 20 cases were L-OHP resistant." (PMID 28076324, 2017). "To understand how PCBP1 mediates L-OHP resistance in colorectal cancer, we focused on the effect of PCBP1 on cellular survival signaling pathways." (PMID 28076324, 2017). "ACE not only increases Fe2+ levels in colorectal cancer cells by targeting iron chaperones PCBP1/2 and reducing their expression but also disrupts the antioxidant system of colorectal cancer cells by targeting GPX4 and inhibiting its enzymatic activity, leading to its ubiquitin-mediated degradation." (PMID 40619432, 2025). "It was observed that poly(C)-binding protein 1 (PCBP1) expression was significantly more elevated in tumor samples from oxaliplatin-refractory patients than in those from responsive patients, suggesting that PCBP1 is a protein marker of oxaliplatin resistance in colorectal cancer cell cultures." (PMID 31828035, 2019). "PCBP1 also can sensitize colorectal cancer to anti-cancer drug." (PMID 30086790, 2018). "These clinical data supported that PCBP1 increases L-OHP resistance in colorectal cancer." (PMID 28076324, 2017). "Furthermore, knockdown of PCBP1 inhibits the activation of Akt in human colorectal cancer cells." (PMID 37303491, 2022). "The analysis of overall survival in colorectal cancer patient samples revealed that patients with high levels of GPX4, PCBP1, and PCBP2 had significantly worse overall survival." (PMID 40619432, 2025). "Taken together, these results demonstrate that PCBP1 plays an important role in L-OHP resistance and can be served as a molecular marker for L-OHP resistance in colorectal cancer patients." (PMID 28076324, 2017). "In conclusion, our findings suggest that PCBP1 is a molecular marker of L-OHP resistance in colorectal cancer and a promising target for colorectal cancer therapy." (PMID 28076324, 2017). "Furthermore, PCBP1, PCBP2, and GPX4 synergistically promoted ferroptosis in colorectal cancer cells." (PMID 40619432, 2025).
colon carcinoma (7 papers, 2018 to 2025). "Results showed the similar physiological significance of PCBP1 in renal tumors to ovary and colon carcinoma analyzed above." (PMID 30086790, 2018). "Specifically, these approaches used distinct reference genes (PCBP1 for DNA-based detection in colon cancer and RPLP0 for RNA-based detection in rectal cancer), which may affect direct comparability between cohorts." (PMID 41019049, 2025). "We previously reported that PCBP1 is broadly downregulated in lung and colon cancers." (PMID 32922440, 2020). "To validate whether PCBP1 and p27 expression are correlated with malignancies and have predictive values to diagnosis, we clarified the relationship between PCBP1 and p27 expression in both ovary and colon tumor tissues." (PMID 30086790, 2018). "Additionally, we investigated the protein expression of PCBP1, PCBP2 and GPX4 in colon cancer patients via immunofluorescence staining." (PMID 40619432, 2025).